ATP2C2 (ATPase secretory pathway Ca2+ transporting 2)
Description:
ATP-driven pump that supplies the Golgi apparatus with Ca(2+) and Mn(2+) ions, both essential cofactors for processing and trafficking of newly synthesized proteins in the secretory pathway. Within a catalytic cycle, acquires Ca(2+) or Mn(2+) ions on the cytoplasmic side of the membrane and delivers them to the lumenal side. The transfer of ions across the membrane is coupled to ATP hydrolysis and is associated with a transient phosphorylation that shifts the pump conformation from inward-facing to outward-facing state. Induces Ca(2+) influx independently of its ATP-driven pump function. At the basolateral membrane of mammary epithelial cells, interacts with Ca(2+) channel ORAI1 and mediates Ca(2+) entry independently of the Ca(2+) content of endoplasmic reticulum or Golgi stores. May facilitate transepithelial transport of large quantities of Ca(2+) for milk secretion via activation of Ca(2+) influx channels at the plasma membrane and active Ca(2+) transport at the Golgi apparatus.
Synonyms: SPCA2; KIAA0703
Tractability: Small molecule: it belongs to a druggable protein family. Antibody: UniProt places it where antibodies can reach, with high confidence; UniProt predicts a signal peptide or a membrane-spanning region; its Gene Ontology location is reachable by antibodies, with medium confidence; the Human Protein Atlas places it where antibodies can reach. PROTAC: ubiquitination databases record sites on it.
Gene: Protein-coding gene on chromosome 16 (84,368,476 to 84,465,779, forward strand). Ensembl gene ENSG00000064270.
Subcellular location: Golgi apparatus, trans-Golgi network membrane; Cell membrane; Basolateral cell membrane
Subcellular location (Human Protein Atlas): Focal adhesion sites; Plasma membrane
Pathways (Reactome):
Transport of small molecules: Ion transport by P-type ATPases
Gene Ontology:
Molecular function: P-type calcium transporter activity; P-type manganese transporter activity; protein binding; ATP binding; ATP hydrolysis activity; nucleotide binding
Biological process: calcium ion transmembrane transport; intracellular calcium ion homeostasis; manganese ion transport; calcium ion transport; manganese ion transmembrane transport
Cellular component: plasma membrane; basolateral plasma membrane; endoplasmic reticulum; Golgi membrane; trans-Golgi network membrane; cytoplasmic side of plasma membrane; cytoplasmic vesicle; Golgi apparatus; membrane; perinuclear region of cytoplasm
Genetic constraint (gnomAD): Loss-of-function variants: 158 observed, 105.29 expected, observed/expected ratio (o/e) 1.5, 90% interval 1.32 to 1.71. The synonymous counts are far from expectation, so gnomAD's model fits this gene poorly and the ratio says little. Missense variants: 1,897 observed, 1,236.6 expected, observed/expected ratio (o/e) 1.53, 90% interval 1.48 to 1.59. Synonymous variants: 786 observed, 514.06 expected, observed/expected ratio (o/e) 1.53, 90% interval 1.44 to 1.62.
Homologues: Orthologues: chimpanzee ATP2C2 (99% identical), macaque ATP2C2 (96% identical), dog ATP2C2 (88% identical), pig ATP2C2 (87% identical), rat Atp2c2 (85% identical), mouse Atp2c2 (84% identical), guinea pig ATP2C2 (82% identical), tropical clawed frog atp2c2 (75% identical), Drosophila melanogaster SPoCk (55% identical), Caenorhabditis elegans pmr-1 (52% identical), zebrafish atp1a3b (29% identical), zebrafish atp1a3a (29% identical), and 7 more. Paralogues in human: ATP2C1 (64% identical), ATP2A1 (34% identical), ATP2A3 (34% identical), ATP2A2 (34% identical), ATP1A2 (29% identical), ATP1A3 (29% identical), ATP1A1 (29% identical), ATP1A4 (29% identical), ATP2B2 (29% identical), ATP2B1 (28% identical), ATP2B3 (28% identical), ATP12A (28% identical), and 9 more.
Diseases named in the same sentence as ATP2C2 in open-access papers:
ATP2C2 is named in the same sentence as 32 diseases in open-access papers, as found by Europe PMC text mining. Sharing a sentence is not in itself a finding about the gene and the disease. The quoted sentences say what the papers report.
breast carcinoma (29 papers, 2012 to 2025). "Gene dysregulation of ATP2C2 has been linked to breast cancers: ATP2C2 (also known as SPCA2) promotes tumor growth by increasing Ca2+ entry through activation of the Orai1 calcium channel." (PMID 33936088, 2021). "This in turn could prevent an abnormal subcellular localization of SPCA1, as is observed for the up-regulation of the related gene ATP2C2 (encoding SPCA2, another member of this family of Ca2+-ATPase pumps) in breast cancer cells." (PMID 23344038, 2013). "A gene-expression study noted that high ATP2C2-expression was associated with worsened patient survival in OSCC, breast cancer, thyroid carcinoma, head-and-neck squamous cell carcinoma, kidney, renal clear cell carcinoma, and lung squamous cell carcinoma." (PMID 36046118, 2021). "In one breast cancer study, ATP2C2 was upregulated compared to normal tissue." (PMID 36046118, 2021). "The Ca2+-ATPase SPCA2, which is encoded by the ATP2C2 gene, is an epithelial marker that inhibits cell-adhesion protein E-cadherin biogenesis in breast cancer cells regardless of estrogen receptor existence (MCF-7 and MDA-MB-231)." (PMID 33806911, 2021).
dyslexia (5 papers, 2015 to 2023). A learning disorder characterized by an impairment in processing written words. "ATP2C2 encodes a magnesium-dependent calcium transporter which fits with reports about disturbed calcium and magnesium levels for dyslexia and other communication disorders." (PMID 34539327, 2021). "This study provides further evidence for genetic variants within DYX1C1 and ATP2C2 as candidates for dyslexia." (PMID 29201552, 2017). "The fourth differentiator of this subgroup was being homozygous for the major allele of rs8053211 in ATP2C2, a gene associated with dyslexia and other language traits, as carriers of one or two copies of the minor allele had a higher risk for diagnosis of AD." (PMID 25880661, 2015). "Regarding a translation of our ATP2C2 finding to a clinical level, it seems to be important that imbalances of magnesium and calcium ions in blood serum were reported in patients with dyslexia and other communication disorders." (PMID 34539327, 2021).
colon cancer (3 papers, 2021 to 2023). "In addition, it was shown that ATP2C2 helps colon cancer cells adapt to hypoxia, prevents cancer cells death, increases proliferation capacity and promotes tumor growth." (PMID 33936088, 2021).
language disorder (3 papers, 2010 to 2022). A category of disorders characterized by an impairment in the development of an individual's language capabilities, which is in contrast to his/her non-verbal intellect. "Both CMIP and ATP2C2 were found to contain common risk variants with a moderate effect size and have additional evidence through the identification of monogenic cases of language disorder." (PMID 35626763, 2022). "ATP2C2 was implicated in language disorders by linkage and association studies, and exactly the same variant was reported previously in a different exome sequencing study for language impairment (LI)." (PMID 33864365, 2021). "In contrast, ATP2C2 was associated with phonological memory in the SLI cohort, but only showed association within the language-impaired group in the general population, suggesting a possible role specifically in individuals with language disorders." (PMID 35626763, 2022).
thyroid cancer (2 papers, 2021). "ATP2C2 can serve as an independent prognostic factor and has better prediction for the survival of thyroid cancer patients." (PMID 33936088, 2021).
asthma (1 paper, 2024). "Genetic phase contributes to disease risk for gene-trait pairs: ATP2C2-COPD (p = 0.000238), FLG-asthma (p = 0.00205), and USH2A-visual impairment (p = 0.0084)." (PMID 38944039, 2024).
chronic obstructive pulmonary disease (1 paper, 2024). A chronic and progressive lung disorder characterized by the loss of elasticity of the bronchial tree and the air sacs, destruction of the air sacs wall, thickening of the bronchial wall, and mucous accumulation in the bronchial tree. "Using longitudinal health records, we additionally identify and replicate a novel association between bi-allelic variation in ATP2C2 and an earlier age at onset of chronic obstructive pulmonary disease (COPD) (p < 3.58 × 10−8)." (PMID 38944039, 2024).
melanoma (1 paper, 2021). A malignant, usually aggressive tumor composed of atypical, neoplastic melanocytes. "We found that the expression level of ATP2C2 is related to the enhanced efficacy of ICIs treatment in melanoma and KIRC." (PMID 33936088, 2021).
primary immunodeficiency (1 paper, 2021). "In the ATP2C2 low-expression group, immune pathways including cytokine–cytokine receptor interaction, hematopoietic cell lineage and primary immunodeficiency were significantly enriched." (PMID 33936088, 2021).
Speech-Language disorder-1 (1 paper, 2024). "Of these, FOXP2 is acknowledged as a monogenic cause for specific Speech-Language disorder-1 (OMIM# 602081) and ATP2C2 as a susceptibility locus (OMIM % 606711) contributing in the etiology of DLD." (PMID 38298611, 2024).
cancer (12 papers, 2017 to 2025). A tumor composed of atypical neoplastic, often pleomorphic cells that invade other tissues. "For instance, HSPA12A is known to regulate inflammatory responses, ATP2C2 plays a critical role in immune microenvironment, and NCS1 is associated with immunotherapy and prognosis of cancer." (PMID 41140666, 2025). "There is a lack of data in the literature highlighting improved patient survival with ATP2C2-upregulation, for any cancer." (PMID 36046118, 2021). "Expression of ATP2C2 in cancer cells is followed by an increase in luminal Ca2+ and initiation of microcalcifications." (PMID 30443032, 2018). "ATP2C2 results in increase Ca2+ influx and promotion of cancer cell motility and proliferation." (PMID 40424447, 2025). "Ingenuity pathway analysis revealed that differentially methylated CpG sites were annotated to genes involved in ‘cell cycling’ (e.g. NDRG1, NEDD1, and MAD1L1), ‘inflammatory diseases’ (e.g. PRTN3), and ‘cancer’ (PCDHA6, MUC4, and ATP2C2)." (PMID 28754985, 2017).
tumor (9 papers, 2013 to 2024). "Further analysis revealed that ATP2C2 was significantly upregulated in various OAC tumor grades and nodal-metastatic stages in both datasets." (PMID 36046118, 2021). "CACNA1D, JPH1, and ATP2C2 were also upregulated in advanced OAC tumor grades and nodal-metastatic stages in both datasets." (PMID 36046118, 2021). "The expression of ATP2C2 in the BRCA samples was significantly higher than that in normal breast tissues or paired breast non-tumor by Wilcoxon rank sum test." (PMID 33936088, 2021). "The low, ATP2C2-expression group had increased numbers of pro-tumor M2 macrophages and decreased numbers of anti-tumor M1 macrophages." (PMID 36046118, 2021). "A total of 76 mRNAs was correlated to lncRNA NR_046683, including ROR2, MTBP and ATP2C2, which are tumor-related protein-coding genes." (PMID 30766487, 2019). "Furthermore, there were significant differences in the transcription levels of CACNA1D, JPH1, and ATP2C2 between various tumor grades and nodal-metastatic stages in both datasets." (PMID 36046118, 2021). "We found that more M1 macrophages infiltrated in ATP2C2 high-expression group compared with ATP2C2 low-expression group, implying that tumor infiltrated macrophages exert immune response functions and exhibit anti-tumor effects." (PMID 33936088, 2021). "In another study, the authors concluded that ATP2C2 antagonizes epithelial mesenchymal transition and suppresses BRCA cell migration and tumor metastasis." (PMID 33936088, 2021).
cardiac diseases (1 paper, 2022). "However, cardiac diseases were independent of the functions of LAMC1, COL4A3, and ATP2C2." (PMID 35924220, 2022).
ATP2C2 also shares sentences with these, for which no sentence is quoted: breast tumors (5 papers); attention deficit-hyperactivity disorder (2); communication disorder (2); head and neck squamous cell carcinoma (2); lung squamous cell carcinoma (2); triple-negative breast carcinoma (2); adenocarcinoma (1); autism (1); Blindness (1); epilepsy (1); esophageal squamous cell carcinoma (1); genetic disorder (1); infection (1); Intellectual disability (1); myopathies (1); neurodevelopmental disorder (1); periodontitis (1); renal clear cell carcinoma (1); Visual impairment (1).